THG1L (tRNA-histidine guanylyltransferase 1 like)
Description:
Adds a GMP to the 5'-end of tRNA(His) after transcription and RNase P cleavage. This step is essential for proper recognition of the tRNA and for the fidelity of protein synthesis (Probable). Also functions as a guanyl-nucleotide exchange factor/GEF for the MFN1 and MFN2 mitofusins thereby regulating mitochondrial fusion. By regulating both mitochondrial dynamics and bioenergetic function, it contributes to cell survival following oxidative stress.
Synonyms: IHG-1; ICF45; FLJ11601; FLJ20546; hTHG1; IHG1; SCAR28; THG1
Tractability: Small molecule: a structure with a bound ligand is known; it has a binding pocket of medium quality. PROTAC: ubiquitination databases record sites on it; its protein half-life has been measured.
Gene: Protein-coding gene on chromosome 5 (157,731,412 to 157,741,449, forward strand). Ensembl gene ENSG00000113272.
Subcellular location: Cytoplasm; Mitochondrion outer membrane
Pathways (Reactome):
Metabolism of RNA: tRNA modification in the nucleus and cytosol
Gene Ontology:
Molecular function: ATP binding; GTP binding; guanyl-nucleotide exchange factor activity; identical protein binding; magnesium ion binding; nucleotidyltransferase activity; protein binding; tRNA guanylyltransferase activity; tRNA binding
Biological process: mitochondrial fusion; protein homotetramerization; response to oxidative stress; stress-induced mitochondrial fusion; tRNA processing; tRNA modification; tRNA 5'-end processing
Cellular component: mitochondrion; transferase complex; cytosol; cytoplasm; mitochondrial outer membrane
Genetic constraint (gnomAD): Loss-of-function variants: 21 observed, 27.15 expected, observed/expected ratio (o/e) 0.77, 90% interval 0.55 to 1.11. The upper end of that interval is the gene's LOEUF score, 1.11, which puts it in group 4 of 6, group 1 being the genes least tolerant of losing a copy. Missense variants: 348 observed, 350.25 expected, observed/expected ratio (o/e) 0.99, 90% interval 0.91 to 1.09. Synonymous variants: 123 observed, 127.74 expected, observed/expected ratio (o/e) 0.96, 90% interval 0.83 to 1.12.
Gene-disease validity (ClinGen):
ClinGen rates the evidence that THG1L causes each of these diseases.
spinocerebellar ataxia, autosomal recessive 28 (autosomal recessive): Limited.
Homologues: Orthologues: chimpanzee THG1L (99% identical), macaque THG1L (97% identical), pig THG1L (91% identical), rabbit THG1L (91% identical), guinea pig THG1L (87% identical), mouse Thg1l (82% identical), dog THG1L (78% identical), rat Thg1l (76% identical), tropical clawed frog thg1l (68% identical), zebrafish thg1l (64% identical), Drosophila melanogaster THG (48% identical).
Diseases named in the same sentence as THG1L in open-access papers:
THG1L is named in the same sentence as 2 diseases in open-access papers, as found by Europe PMC text mining. Sharing a sentence is not in itself a finding about the gene and the disease. The quoted sentences say what the papers report.
cervical cancer (1 paper, 2015). A primary or metastatic malignant neoplasm involving the cervix. "For example, THG1L which has been up-regulated by PDGFBB inhibition has been shown to modulate cell cycle progression and cell proliferation of cervical cancer cells." (PMID 25311137, 2015).
THG1L also shares sentences with these, for which no sentence is quoted: brain disorder (1 paper).